WWOX (WW domain containing oxidoreductase)
Diseases named in the same sentence as WWOX in open-access papers (continued):
Sharing a sentence is not in itself a finding about the gene and the disease.
osteosarcoma (continued). "To determine whether WWOX plays a role in the survival of osteosarcoma cells, we overexpressed WWOX and knocked down WWOX expression in U2OS, SAOS2, and MG-63 cells and examined apoptosis rates using flow cytometry." (PMID 28977834, 2017). "Given the lack of FRA16D breakage and WWOX loss in some osteosarcomas we have investigated alternate mechanisms for suppressing WWOX expression." (PMID 29152092, 2017). "Nevertheless, the lack of correlation between WWOX expression and osteosarcoma patient prognosis suggests that its loss is an early event in cancer pathogenesis with the phenotypic results of its deletion not contributing directly to patient demise." (PMID 29152092, 2017). "It has been shown that osteosarcoma is the dominant phenotype in WWOX gene knockout mice." (PMID 29152092, 2017). "Furthermore, decreased WWOX expression promoted angiogenesis in osteosarcoma by upregulating these same genes." (PMID 28977834, 2017). "Our data also showed that WWOX inhibited the invasion of osteosarcoma cells." (PMID 28977834, 2017). "We hypothesized that the lncRNA PARTICLE might provide an alternative path for inactivation of WWOX in osteosarcoma where the fragile site remained intact." (PMID 29152092, 2017). "Furthermore, overexpression of WWOX inhibited the metastasis of human osteosarcoma and reduced tumor sizes in a nude mouse model." (PMID 28977834, 2017). "We confirmed that WWOX inhibited RUNX2 expression in osteosarcoma cells." (PMID 28977834, 2017). "We then examined whether WWOX expression in osteosarcoma tissues was predictive of disease-free survival (DFS) in osteosarcoma patients using Cox regression analysis." (PMID 28977834, 2017). "Additionally, WWOX immunoreactivity was reduced in 58% of osteosarcoma specimens, while WWOX expression was strong in all the normal bone specimens." (PMID 28977834, 2017). "Moreover, other authors further emphasize that while WWOX and RUNX2 are both critical in bone biology and osteosarcoma pathology, where RUNX2 overexpression is typically linked to higher tumor grade, metastasis, and poor prognosis, their roles have not been similarly delineated in ES." (PMID 41141138, 2025). "To determine whether WWOX expression is epigenetically regulated by DNA methylation in osteosarcoma cells, we treated MG-63 cells with the DNA methylation inhibitors hydralazine and 5-Aza-CdR alone or in combination and measured WWOX mRNA and protein levels using qRT-PCR and Western blotting." (PMID 28977834, 2017). "In the context of bone tumor research, the interaction between WWOX and RUNX2 has been extensively studied in osteosarcoma." (PMID 41141138, 2025). "Here, we found that WWOX inhibited the expression of RUNX2, bcl-2, OPN, and VEGF in osteosarcoma cells." (PMID 28977834, 2017). "WWOX promoted apoptosis and inhibited invasion and expression of bcl-2, OPN, RUNX2, and VEGF in osteosarcoma cells in vitro." (PMID 28977834, 2017). "The fact that WWOX deletion does not occur frequently but that loss of its expression is common suggests that factors influencing the epigenetic alterations of this gene might also be involved in the pathogenesis of osteosarcoma." (PMID 29152092, 2017). "Consequently, although the inverse correlation between WWOX and RUNX2 is well documented in osteosarcoma, direct evidence of a similar relationship in ES is currently under-characterized and remains to be firmly established." (PMID 41141138, 2025). "The rationale for focusing on this axis lies in prior evidence showing that WWOX suppresses RUNX2 activity and thereby reduces metastatic potential in osteosarcoma, raising the possibility that a similar mechanism may exist in ES." (PMID 41141138, 2025). "WWOX sequesters p73 in the cytoplasm (in NIH3T3 mouse fibroblasts and human breast MCF7 cells), and cytoplasmic p73 contributes to the proapoptotic activity of WWOX (in human osteosarcoma SAOS-2 cells)." (PMID 33946771, 2021).
osteosarcoma (continued). "To determine whether WWOX plays a role in osteosarcoma cell invasion, we examined the invasion capacity of U2OS, SAOS2, and MG-63 cells with WWOX overexpression or knockdown using the Boyden chamber assay." (PMID 28977834, 2017). "To characterize the regulatory cascade involving WWOX, bcl-2, OPN, RUNX2, and VEGF in osteosarcoma cells, we transfected MG-63 cells overexpressing WWOX with bcl-2 or RUNX2 expression plasmids and measured WWOX, bcl-2, OPN, RUNX2, and VEGF expression using Western blotting." (PMID 28977834, 2017). "In addition, WWOX inhibited the expression of bcl-2, OPN, RUNX2, and VEGF in osteosarcoma cells, while bcl-2 increased VEGF expression and RUNX2 increased VEGF and OPN expression in MG-63 cells." (PMID 28977834, 2017). "Furthermore, we showed that WWOX also inhibited the expression of bcl-2, OPN, and VEGF in osteosarcoma cells." (PMID 28977834, 2017). "In conclusion, we found that the inhibition of WWOX expression, which was due at least in part to DNA methylation, inhibited apoptosis, promoted invasion, upregulated bcl-2, OPN, RUNX2, and VEGF expression, and increased MVD in osteosarcoma cells." (PMID 28977834, 2017). "WWOX overexpression decreased, while WWOX knockdown increased, the numbers of migrated osteosarcoma cells compared to the normal and negative controls." (PMID 28977834, 2017). "To determine whether WWOX regulates bcl-2, RUNX2, VEGF, and OPN expression in osteosarcoma cells, we used Western blotting and qRT-PCR to examine protein and mRNA levels of these factors in U2OS, SAOS2, and MG-63 cells with WWOX overexpression or knockdown." (PMID 28977834, 2017). "WWOX overexpression decreased, while WWOX knockdown increased, RUNX2, bcl-2, VEGF, and OPN protein and mRNA levels in osteosarcoma cells compared to the normal and negative controls." (PMID 28977834, 2017). "An inverse WWOX and RUNX2 interaction was not as clear in human osteosarcomas as in cell lines." (PMID 36271927, 2022).
prostate carcinoma (23 papers, 2007 to 2026). A carcinoma that arises from epithelial cells of the prostate gland. "In this study, we investigated the associations between the polymorphisms of WWOX, clinicopathologic features of prostate cancer (PCa), and risk of postoperative biochemical recurrence (BCR)." (PMID 37324196, 2023). "The methylation rate of the WWOX promoter has been reported to be associated with the loss of WWOX expression in breast, lung, bladder, pancreatic, and prostate cancers." (PMID 27655721, 2016). "Activated tyrosine kinase Cdc42-associated kinase (ACK1) promotes prostate cancer progression, via binding and phosphorylating WWOX at Tyr287 for polyubiquitination and proteosomal degradation." (PMID 27999774, 2016). "Genome-wide scan analysis studies conducted on the rs1079635 which is in intron 7 of WWOX have also reported that this region demonstrated a strong association with prostate cancer susceptibility." (PMID 27655721, 2016). "WWOX gene, a tumor suppressor gene, that has been reported to play a role in prostate cancer, showed evidence of association (rs3751832, p = 0.0009) in our study sample." (PMID 17903305, 2007). "Therefore, further translational studies on WWOX expression and its association with prostate cancer behavior are needed to validate the effect of genetic signature on the prognosis of tumor recurrence." (PMID 37324196, 2023). "Recently, genome-wide linkage analysis studies for SNPs in prostate cancer patients have revealed that WWOX polymorphic variants may be associated with cancer susceptibility." (PMID 28426730, 2017). "The result showed that the expression of WWOX mRNA was significantly lower in 9 cancer types, including thyroid, bladder, lung, endometrium, kidney, breast, and prostate cancers." (PMID 41124647, 2026). "In prostate cancer, WWOX mediates G1 cell cycle arrest by downregulating cyclin D1 expression, which in turn suppresses the proliferation of 22Rv1 prostate cancer cells and inhibits tumor growth in nude mice." (PMID 41228229, 2025). "Treatment with either 5-aza-2′-deoxycytidine or trichostatin A, a histone deacetylase inhibitor, markedly enhances the expression of WWOX mRNA and protein in prostate cancer-derived cells." (PMID 41228229, 2025). "The intracellular tyrosine kinase, activated Cdc42-associated kinase (ACK1), promotes tumor progression in prostate cancer and hepatocellular carcinoma (HCC) by negatively regulating WWOX." (PMID 41228229, 2025). "The absence or reduction of WWOX expression has been indicated to be involved in prostate carcinoma." (PMID 36271927, 2022). "WWOX expression is also inhibited by its hypermethylation in some cancer cells, and the tyrosine kinase Ack-1 phosphorylates WWOX on its tyrosine 287, which induces its polyubiquitination and thereby its degradation by the proteasome in prostate cancer." (PMID 33946771, 2021). "In coincidence with its tumor suppressor function, overexpression of WWOX protein in malignant lung, breast, pancreatic, cervical, and prostate cancer cells suppresses cell growth and increases cell apoptosis." (PMID 33195192, 2020). "The C1q complex is not only involved in recognition of complement activating elements, but also in regulation of autoimmune diseases and in prostate cancer via the activation of tumor suppressor molecule WOX1 (WW-domain containing oxidoreductase)." (PMID 33718121, 2020). "ACK1 not only activates survival kinase AKT and up-regulates the activity of hormone receptor androgen receptor but also induces tumor suppressor WWOX degradation in hormone-driven breast and prostate cancers." (PMID 26498357, 2017). "Activated ACK1 has been detected in advanced human prostate cancers where it has been shown to phosphorylate three cancer relevant substrates in prostate cancer cell lines: WWOX, AKT, and androgen receptor." (PMID 22615583, 2012). "In addition, WWOX polymorphisms are associated with postoperative recurrence and tumor aggressiveness in HCC and prostate cancer." (PMID 41228229, 2025).
prostate carcinoma (continued). "Additionally, in prostate cancer-derived cells, DNA hypermethylation within the WWOX regulatory region contributes to the downregulation of WWOX expression." (PMID 41228229, 2025). "Some authors have suggested that the tumor suppressor function of WWOX may be important during the phase of prostate cancer progression when cancer cells shift to be androgen-independent." (PMID 36271927, 2022). "Moreover, it was reported that WWOX overexpression induced cell apoptosis and suppressed prostate cancer growth in vitro and in vivo." (PMID 36271927, 2022). "Yet in breast and prostate cancer cell lines, extracellular C1q was involved in initiating a signaling pathway that activates the expression of the WWOX (WW domain-containing oxidoreductase) tumor-suppressor gene." (PMID 40370471, 2025). "HA induces WWOX-Hyal-2-SMAD4 complex formation and bubbling cell death in human prostate cancer DU145 cells." (PMID 33946771, 2021). "In prostate cancer, Ack1 stimulates prostate tumorigenesis in part by negatively regulating the proapoptotic tumor suppressor, the WW domain containing oxidoreductase (Wwox)." (PMID 21454924, 2011). "WWOX has been well-characterized as a tumor suppressor, following studies that its expression is frequently lost as a result of translocations within the fragile site FRA16D, including prostate cancers." (PMID 19774227, 2009).
epilepsy (22 papers, 2014 to 2025). A brain disorder characterized by episodes of abnormally increased neuronal discharge resulting in transient episodes of sensory or motor neurological dysfunction, or psychic dysfunction. "Subsequent genetic testing revealed the presence of an epilepsy-associated novel mutation: c.991C>A (amino acid change: p.Ser304Tyr) in the WWOX gene." (PMID 39416860, 2024). "Recent evidence has revealed that mutations in WWOX are associated with epilepsy, with variant types including missense variants, nonsense variants, frameshift variants, duplications, and splice site mutations." (PMID 39416860, 2024). "Early lethal microcephaly syndrome with epilepsy, neurodegeneration and profound growth retardation have been reported in the pediatric patients with autosomal recessive homozygous mutation of WWOX." (PMID 37897534, 2023). "The WWOX knockout (KO) mouse model exhibits features that phenocopy some symptoms observed in individuals with WWOX variants such as epilepsy, structural brain malformation, and learning impairments." (PMID 33916893, 2021). "Several animal models of WWOX deficiency have been described in the literature, however, two models in particular report phenocopy epilepsy." (PMID 33916893, 2021). "Children with SCAR12, mostly due to missense mutations in WWOX, display a milder phenotype including ataxia and epilepsy." (PMID 34747138, 2021). "In two other families, cerebellar ataxia with epilepsy and mental retardation are consequences of missense mutation in the WWOX gene." (PMID 27495153, 2016). "Early lethal microcephaly syndrome with epilepsy, cerebellar ataxia, mental retardation and profound developmental delay have been observed in pediatric patients with autosomal recessive mutation of WWOX." (PMID 37897534, 2023). "Loss-of-function mutations in both alleles of WWOX gene lead to autosomal recessive abnormalities in pediatric patients from consanguineous families, including microcephaly, cerebellar ataxia with epilepsy, mental retardation, retinal degeneration, developmental delay and early death." (PMID 32000863, 2020). "Indeed, WWOX germline mutations were found associated with developmental retardation, ataxia, early onset of epilepsy and intellectual deficiency." (PMID 30370248, 2018). "WWOX deficiency leads to epilepsy, mental retardation and early death." (PMID 27551439, 2015). "Deficiency of WWOX/Wwox gene due to point mutations or homozygous nonsense mutation may result in childhood onset autosomal recessive cerebellar ataxia and epilepsy, growth retardation, microcephaly with seizure, retinal degeneration, and early death at 16 months of age." (PMID 30158849, 2018). "Among the other 21 de novo variants in curated epilepsy or seizure-associated genes, two deep intronic variants on SOX5 (IS05) and WWOX (IS06) had high CADD scores above 15 (17.92 and 17.91, respectively)." (PMID 35937050, 2022). "Transcriptional analysis of neurospheres derived from WWOX KO neural stem cells reveals alterations in the expression of genes related to neurological disorders, CNS development, and epilepsy." (PMID 33916893, 2021). "One of the genes found to have differential expression during development in the epilepsy cluster was WWOX, which was expressed early in prenatal development, was downregulated, and reappeared later in post-natal developmental stages (long-term culture of cortical spheroids)." (PMID 34831305, 2021). "The molecular function and importance of WWOX in epilepsy and ataxia is largely unknown and is currently under investigation by several labs." (PMID 30370248, 2018). "Despite these studies, it is evident that detailed studies uncovering the molecular and cellular roles of WWOX in pediatric epilepsy are still lacking." (PMID 33916893, 2021).
ovarian carcinoma (20 papers, 2004 to 2026). A malignant neoplasm originating from the surface ovarian epithelium. "In order to examine new ideas for gene therapy in ovarian cancer, the specific mechanism underlying the effects of the WW domain containing oxidoreductase (WWOX) gene on cell cycle regulation and apoptosis in human ovarian cancer stem cells was investigated." (PMID 25891642, 2015). "The aim of the present study was to investigate the impact of the WW domain-containing oxidoreductase (WWOX) gene on the mechanisms underlying epithelial-mesenchymal transition (EMT) in human ovarian cancer stem cells." (PMID 24959289, 2014). "The WWOX gene was observed to be associated with the occurrence and development of ovarian cancer; normal expression of the WWOX gene suppresses the occurrence of ovarian cancer." (PMID 24137423, 2013). "Thirty percent of ovarian carcinomas (133/444) showed loss of WWOX protein expression while 70% (311/444) demonstrated positive staining including cases with very strong staining." (PMID 15982416, 2005). "Taken together the data indicates that a gene, likely WWOX, located at 16q23-24 is associated with a worse prognosis in ovarian cancer." (PMID 15982416, 2005). "Furthermore, high WWOX expression is associated with longer overall survival and progression-free survival in ovarian cancer patients treated with paclitaxel." (PMID 41228229, 2025). "In addition, studies have identified several SNPs in WWOX as potential risk factors for several cancers such as thyroid carcinomas, esophageal adenocarcinoma, pancreatic and ovarian cancer." (PMID 27655721, 2016). "Alteration of WWOX has been observed in many tumors, including breast, ovarian, prostate, lung, hepatocellular, gastric, and other cancers, and loss or reduction of its expression is reported to be correlated with worse clinical prognosis such as breast and ovarian cancer." (PMID 27190995, 2016). "Moreover, loss of WWOX expression was observed in OC, especially epithelial ovarian cancer (EOC)." (PMID 27190995, 2016). "WW domain containing oxidoreductase (WWOX) makes epithelial ovarian cancer cells more sensitive to paclitaxel via ER stress-induced apoptosis." (PMID 36890838, 2023). "In ovarian carcinoma cell lines, WWOX was found to act as a tumor suppressor by modulating the interaction of tumor cell integrin-α3 with extracellular matrix components (fibronectin) and promoting apoptosis in detached cells." (PMID 33129329, 2020). "Our data suggest that WWOX regulates taxane response in ovarian cancer by modulating the drug-related ER stress response." (PMID 28749468, 2017). "Here, through modulating WWOX expression in ovarian cancer cells we show that WWOX influences paclitaxel-induced cell death through ER stress pathway and an intact IRE-1 arm of UPR is crucial for WWOX to function." (PMID 28749468, 2017). "We screened several ovarian cancer cells to detect WWOX expression and found endogenous protein expression in OVCAR-4, OVCAR-8, SKOV-3 and A2780 cell lines." (PMID 28749468, 2017). "The present study aimed to investigate the effects of the WW domain-containing oxidoreductase (WWOX) gene on the stem cell properties of human ovarian cancer stem cells." (PMID 25789010, 2015). "The results demonstrated that following transfection of the WWOX gene, the rate of apoptosis in ovarian cancer stem cells was significantly increased." (PMID 25891642, 2015). "In conclusion, the present study demonstrated that the WWOX gene can be stably expressed in ovarian cancer stem cells and that it inhibits the proliferation of ovarian cancer stem cells." (PMID 25891642, 2015). "In the current study, the plasmid pcDNA3.1-WWOX was transfected into human ovarian cancer stem cells to determine the effects of WWOX overexpression on stem cell properties." (PMID 25789010, 2015).